HCP5 (HLA complex P5)
Diseases named in the same sentence as HCP5 in open-access papers (continued):
Sharing a sentence is not in itself a finding about the gene and the disease.
lymph node metastasis (3 papers, 2018 to 2021). "Moreover, the high expression of serum HCP5 was related to differentiation, lymph node metastasis, and nerve invasion." (PMID 34222007, 2021). "Besides, glutathione-disulfide reductase (GSR), human leukocyte antigen complex P5 (HCP5), and achaete-scute family bHLH transcription factor 1 (ASCL1) were upregulated in the SCLC patients with lymph node metastasis." (PMID 30364292, 2018). "Here, 186 upregulated (e.g., GSR, HCP5) and 144 downregulated DEGs (e.g., MET, GRM8, and DACH1) were identified between the SCLC patients with lymph node metastasis and without lymph node metastasis." (PMID 30364292, 2018).
lymphoma (3 papers, 2019 to 2022). A malignant (clonal) proliferation of B- lymphocytes or T- lymphocytes which involves the lymph nodes, bone marrow and/or extranodal sites. "In our study, the association, although very preliminary, of HCP5 variant with lymphoma development is a promising result." (PMID 30882006, 2019). "In fact, studies have already found that PRKCQ-AS1 and HCP5, which are included in our ELncSig, play important roles in the process of lymphoma, while other lncRNAs were revealed in DLBCL for the first time." (PMID 35874768, 2022). "HCP5 rs3099844 was associated with anti-SSA (P = 0.006, OR = 3.07) and anti-SSB (P = 0.005, OR = 2.66) antibodies, severity of focus score (P = 0.03, OR = 12), and lymphoma development (P = 0.002, OR = 7.23)." (PMID 30882006, 2019).
multiple myeloma (3 papers, 2022 to 2024). "HCP5/miR-128-3p/PLAGL2 signaling was associated with an increased risk of multiple myeloma through altered Wnt/-catenin/cyclin D1 signaling." (PMID 36793341, 2022).
non-small cell lung carcinoma (3 papers, 2019 to 2021). A group of at least three distinct histological types of lung cancer, including non-small cell squamous cell carcinoma, adenocarcinoma, and large cell carcinoma. "Besides, HCP5 and PSMB8-AS1 have been demonstrated could be the tumor-infiltrating immune-related lncRNA signature of non-small cell lung cancer and closely associated with outcome and immune cell infiltrates." (PMID 33584801, 2020).
Obesity (3 papers, 2019 to 2024). Accumulation of substantial excess body fat. "In contrast to the more common observation of hypomethylation, HCP5 hypermethylation was associated with obesity and BMI in an epigenome-wide association study of adiposity in Ghanaian African migrants using whole blood to measure DNA methylation." (PMID 31137555, 2019). "Recent studies have identified differentially methylated sites within, or neighboring, the HCP5 gene sequence associated with epigenetic regulation of various disease phenotypes (obesity, SLE) and in response to fetal development, aging, HIV infection, and vaccination." (PMID 31137555, 2019). "The HCP5 gene sequence is a differentially methylated site associated with the epigenetic regulation of some disease phenotypes, such as obesity and SLE, and it may also act in response to fetal development, aging, HIV or influenza infection, and vaccination." (PMID 31137555, 2019). "Methylomic studies have associated HCP5 strongly with HIV progression, SLE, ankylosing spondylitis (AS) and obesity." (PMID 31137555, 2019). "Other nominally significant associations were established between WHOCS scales and: IFNL4 rs12979860, ACEIs, obesity, ARA-II, HCP5 rs2395029, ACE rs1799752, DPP4 rs17574, HMOX1 rs2071746, IL10 rs1800896, IL6 rs1818879, NFKB1 rs28362491, and MX1 rs469390." (PMID 35636966, 2022).
schizophrenia (3 papers, 2017 to 2023). A major psychotic disorder characterized by abnormalities in the perception or expression of reality. "Among these, two lncRNAs, ZNF883 and HCP5, may play a role in the pathogenesis of schizophrenia." (PMID 37383091, 2023). "HCP5 can be used as an immune-related marker for various human malignancies; however, its role in schizophrenia has not been elucidated." (PMID 37383091, 2023).
toxic epidermal necrolysis (3 papers, 2018 to 2024). Toxic epidermal necrolysis (TEN) is an acute and severe skin disease with clinical and histological features characterized by the destruction and detachment of the skin epithelium and mucous membranes. "In a previous study, one genetic variant (rs3099844) of HCP5 was found to contribute to nevirapine‐induced Stevens Johnsons Syndrome/toxic epidermal necrolysis susceptibility in a population from Mozambique, suggesting the immune‐associated function of HCP5." (PMID 29992774, 2018). "Variants of the HCP5 gene are associated with an increased risk of developing Stevens–Johnson syndrome (SJS) and toxic epidermal necrolysis (TEN), which are severe and potentially life-threatening cutaneous drug reactions." (PMID 38792557, 2024).
viral infection (3 papers, 2014 to 2020). "Hence, it is possible that HCP5 carriers mount a strong immune reaction to viral infection that, in genetically susceptible individuals, could lead to excessive inflammation." (PMID 25369137, 2014). "Although increased HCP5 levels seem to be a common event upon viral infection and in response to interferon stimulation and some cancers, the consequences of HCP5 upregulation are diverse." (PMID 31137555, 2019).
acute myelogenous leukemia (2 papers, 2021 to 2022). "We subsequently found in vitro that silencing of HCP5 significantly affected the proliferation of KG-1 cells derived from the human acute myelogenous leukemia cell line." (PMID 36147489, 2022).
bladder cancer (2 papers, 2022). "HCP5 is a novelty diagnostic and prognostic biomarker in gastric and bladder cancers." (PMID 36248798, 2022). "Moreover, an increasing number of studies have revealed the importance of HCP5 in tumorigenesis development, such as up-regulation of HCP5 could promote cell invasion and migration in human bladder cancer." (PMID 35399723, 2022).
chronic kidney disease (2 papers, 2021 to 2022). Impairment of the renal function secondary to chronic kidney damage persisting for three or more months. "Besides, HCP5 was proposed to be one of the potential prognostic biomarkers for predicting the risk of chronic kidney disease (CKD)." (PMID 34187448, 2021).
herpes zoster (2 papers, 2020 to 2022). A common dermal and neurologic disorder caused by reactivation of the varicella-zoster virus that has remained dormant within dorsal root ganglia, often for decades, after the patient's initial exposure to the virus in the form of varicella (chickenpox). "LncRNA HCP5 is mainly expressed in the immune system and often considered to be associated with herpes zoster and other serious skin reactions." (PMID 35122570, 2022). "Genetic variation in the HLA region (HLA Complex P5—HCP5) was linked to susceptibility to herpes zoster resulting from VZV reactivation." (PMID 32075270, 2020).
laryngeal squamous cell carcinoma (2 papers, 2021 to 2022). A squamous cell carcinoma that arises from the larynx. "Nevertheless, the effect and regulatory mechanism of HCP5 in laryngeal squamous cell carcinoma (LSCC) remains unknown." (PMID 36248798, 2022).
myocardial infarction (2 papers, 2022 to 2023). Gross necrosis of the myocardium, as a result of interruption of the blood supply to the area, as in coronary thrombosis. "Mechanically, HLA complex P5 (HCP5) and myocardial infarction associated transcript (MIAT), upregulated the expression of PD-L1/CD274 by sponging miR-150-5p, which is regulated by the transcriptional axis of lip-polysaccharides (LPS) -CCCTC binding factor (CTCF)." (PMID 36810034, 2023).
sarcoma (2 papers, 2021 to 2022). A usually aggressive malignant neoplasm of the soft tissue or bone. "One bioinformatic analysis reported that the overexpression of the lncRNAs ADAM6, C5orf58, CXCR2P1, FCGR2C, HCP5, HLA-H, NAPSB, NCF1B, and NCF1C reduced the sensitivity of sarcoma to ICIs." (PMID 36326232, 2022). "The expression of nine ICLs, ADAM6, C5orf58, CXCR2P1, FCGR2C, HCP5, HLA-H, NAPSB, NCF1B and NCF1C, was further investigated in different cancer types, including sarcoma." (PMID 34178688, 2021).
systemic lupus erythematosus (2 papers, 2019 to 2021). An autoimmune multi-organ disease typically associated with vasculopathy and autoantibody production. "In our previous works, we described associations between SNPs in the STAT4, IL10, TRAF3IP2, and HCP5 (HLA complex P5) genes and systemic lupus erythematosus (SLE) susceptibility." (PMID 30882006, 2019).
allergic rhinitis (1 paper, 2022). Inflammation of the nasal mucous membranes caused by an IgE-mediated response to external allergens. "HCP5/miR-16/ATXN2L are associated with regulatory T-cell differentiation and function, and regulated IL-13-induced inflammatory cytokine and mucus production in allergic rhinitis." (PMID 35122570, 2022).
autoimmune thyroid disease (1 paper, 2020). Inflammatory disease of the thyroid gland due to autoimmune responses leading to lymphocytic infiltration of the gland. "The HCP5 polymorphism rs3094228 investigated in this study has previously been associated with susceptibility to GD in a Polish cohort, and an association has been demonstrated between the C allele and thyroid peroxidase antibody levels in autoimmune thyroid disease." (PMID 32501499, 2020).
celiac disease (1 paper, 2022). An autoimmune genetic disorder with an unknown pattern of inheritance that primarily affects the digestive tract. "The most significantly up-regulated genes in celiac disease were TAP1, HLA-E, HCP5, STAT1, GBP1, STAT1, LOC100419583, and GBP4 and the down-regulated ones were IDS, PKIB, FBXO2, OXT, and ADI1." (PMID 36011206, 2022).
diabetic nephropathy (1 paper, 2021). "However, the function of HCP5 in diabetic nephropathy (DN) is unclear." (PMID 34187448, 2021).
endometriosis (1 paper, 2025). The growth of functional endometrial tissue in anatomic sites outside the uterine body. "While the elevated expression of HCP5 has been linked to poorer survival in several cancers, in the context of endometriosis its overexpression could reflect persistent inflammatory signaling or local immune alterations that favor chronicity of ectopic tissue." (PMID 40863222, 2025).
gastritis (1 paper, 2021). Inflammation of the stomach. "In addition, due to the limited sample size of patients with gastritis, it was necessary to increase further gastritis samples and long-term observation of patients with gastritis to obtain new insights into the potential mechanism of the diagnostic and prognostic value of HCP5." (PMID 34222007, 2021). "At the same time, we also detected the expression level of serum HCP5 in gastritis and normal controls." (PMID 34222007, 2021). "Compared with the typical clinical diagnostic indicators CEA and CA199, the results showed that serum HCP5 could better distinguish gastritis patients from healthy donors." (PMID 34222007, 2021). "Collectively, the results indicated that serum HCP5 could distinguish gastritis patients from healthy donors." (PMID 34222007, 2021). "At the same time, we detected expression levels of serum HCP5, CEA, and CA199 in 21 patients with gastritis patients and 21 healthy donors, respectively." (PMID 34222007, 2021).
herpes infection (1 paper, 2019). "Other SNVs within the HCP5 gene or within 2.5 kb of the 5′ or 3′ UTR region are useful association markers for various diseases including myositis, herpes infection, cancer, and risk of relapse after transplantation." (PMID 31137555, 2019).
HIV-1 infection (1 paper, 2023). The type species of lentivirus and the etiologic agent of acquired immunodeficiency syndrome (AIDS). "HCP5 harbors multiple single nucleotide variants that are associated with HIV-1 control, yet the role of HCP5 expression levels in HIV-1 infection had not previously been established." (PMID 38168352, 2023).
Infertility (1 paper, 2025). "In the non-ART sample, we identified genome-wide significant fetal effects on fetal survival for SNPs within regions harboring genes relevant to infertility and fetal development, such as MDC1, MICB, HCP5, and NOTCH4." (PMID 41325449, 2025).
influenza (1 paper, 2019). An acute viral infection of the respiratory tract, occurring in isolated cases, in epidemics, or in pandemics; it is caused by serologically different strains of viruses (influenzaviruses) designated A, B, and C, has a 3-day incubation period, and usually lasts for 3 to 10 days. "The differential methylation of PTPRN2 and HCP5 in the endometrium is an interesting connection, given that they both were differentially methylated in a system-wide association study between DNA methylation, gene expression, and humoral immune response to influenza." (PMID 31137555, 2019). "While this was the case for HLA-B, the reverse was observed for HCP5 in humoral immune response to influenza." (PMID 31137555, 2019). "For example, in some instances, HCP5 might be upregulated, whereas class I HLA genes are downregulated as exemplified in the study of humoral immune response to influenza." (PMID 31137555, 2019).
leukemia (1 paper, 2021). A malignant (clonal) hematologic disorder, involving hematopoietic stem cells and characterized by the presence of primitive or atypical myeloid or lymphoid cells in the bone marrow and the blood. "We next conducted the qRT-PCR experiment to detect the expression levels of HCP5 in human bone marrow stromal cell line HS-5, and leukemia cell lines THP-1 and K562." (PMID 34187569, 2021).
leukopenia (1 paper, 2019). "Overall, the association between HCP5 rs3099844 SNP and specific laboratory features (autoantibodies and leukopenia) as well as with the severity of the FS leads to hypothesize a role of this variant in a more aggressive pattern of disease." (PMID 30882006, 2019).
liver disease (1 paper, 2017). "The genetic factors that play a role in late-stage liver disease remain controversial, although several studies have shown that variants in MICA, DEPDC5, HCP5 and PNPLA3 affect HCC development." (PMID 28928439, 2017).
myocardial ischemia (1 paper, 2024). A disorder of cardiac function caused by insufficient blood flow to the muscle tissue of the heart. "In an animal model of myocardial ischemia/reperfusion, DEX alleviated myocardial mitochondrial apoptosis through a pathway involving the lncRNA HCP5/miR-29a/MCL1 axis and activation of Janus kinase 2/signal transducer and activator of transcription 3 signaling." (PMID 39881865, 2024).
pericarditis (1 paper, 2014). An inflammatory process affecting the pericardium. "STAT4, that showed the strongest association with the disease, was also associated with a higher risk to develop pericarditis, while HCP5 SNPs resulted associated with anti-Ro/SSA, anti-dsDNA and aCL." (PMID 25369137, 2014). "The genotype/phenotype correlation analysis showed several associations including a higher risk to develop pericarditis with STAT4, and an association between HCP5 rs3099844 and anti-Ro/SSA antibodies." (PMID 25369137, 2014).
polycystic ovarian syndrome (1 paper, 2021). "HCP5 is a lncRNA that is involved in the pathogenesis of polycystic ovarian syndrome (PCOS)." (PMID 33768092, 2021).
prostate tumour (1 paper, 2023). "A single study investigating HCP5 in PCa using tissues and cell lines, found high expression of HCP5 to be positively correlated to prostate tumour metastasis." (PMID 38052806, 2023).
pulpitis (1 paper, 2023). Inflammation of the dental pulp. "Accordingly, HCP5 may be associated with autophagy and irreversible pulpitis." (PMID 37208635, 2023). "HCP5 may target hsa-miR-214-3p and compete with MAPK1, thus playing a role in cell autophagy and the modulation of irreversible pulpitis." (PMID 37208635, 2023). "We established ceRNA networks including 9 hub lncRNAs (HCP5 and AC112496.1 ↑; FENDRR, AC099850.1, ZSWIM8-AS1, DLX6-AS1, LAMTOR5-AS1, TMEM161B-AS1 and AC145207.5 ↓), which were validated by a qRT‒PCR ﻿analysis of pulp tissue from patients with irreversible pulpitis." (PMID 37208635, 2023).
squamous cell carcinoma (1 paper, 2019). A carcinoma arising from squamous epithelial cells. "HCP5 has been associated with various other cancers including cutaneous melanoma, HPV-infected head and neck squamous cell carcinoma, squamous cell carcinoma cells, HCV-induced liver cancer, and upper tract urothelial carcinoma in which ceRNA cross-talk has yet to be tested." (PMID 31137555, 2019).
thyroid (1 paper, 2022). "Human leukocyte antigen (HLA) complex P5 (HCP5) has recently been shown to be a tumor suppressor in the formation of PTC, which accounts for 80–85% of thyroid malignancies." (PMID 36793341, 2022).